CDC6 (cell division cycle 6)
Diseases named in the same sentence as CDC6 in open-access papers (continued):
Sharing a sentence is not in itself a finding about the gene and the disease.
tumor (continued). "Moreover, gene amplification of Cdc6 as well as of E2F (an upstream regulator of Cdc6) have also been found to be a key feature in tumours overexpressing Cdc6, further highlighting this event as a potential driver of tumourigenesis." (PMID 32010971, 2020). "Positive-cdc6 expression correlated with tumor grade (P=0.012)." (PMID 27246979, 2016). "Cdc6 staining was localized in the cytoplasm and nucleus of tumor cells." (PMID 27246979, 2016). "There are significant correlation between Cdc6 up-regulation and higher tumor grade." (PMID 27246979, 2016). "Cdc6 plays an important role in the malignant progression of tumor." (PMID 27246979, 2016). "A similar analysis of tumour cells growing anchorage-dependently revealed a very weak correlation between Chk1 S296 phosphorylation and Cdc6 (R2 = 0.219) but a similar correlation between total Chk1 protein and Cdc6 (R2 = 0.539) as observed in the xenograft samples." (PMID 27775084, 2016). "The genes CCND1, CDC6 and Bmi-1, when overexpressed, promote the proliferation of tumor cells." (PMID 26317630, 2015). "However, about 15% progenies derived from cdc6 and c-myc double transgenic lines displayed tumor-like protruding structure on the skin surface (especially on the pectoral fin) from at only 8 dpf." (PMID 25051368, 2014). "Furthermore, elevated CDC6 expression may promote tumor cell proliferation by regulating the cell cycle (Borlado and Méndez, 2008), while high LCK expression may enhance T cell activity, thereby improving immunotherapy efficacy." (PMID 40708839, 2025). "In addition, CDC6 expression in UCEC was higher in patients with tumor invasion (≥50%)." (PMID 39684684, 2024). "Therefore, CDC6 inhibition in tumor cells might be an effective target for enhancing tumor radiosensitivity." (PMID 35875060, 2022). "Moreover, the relationships between CDC6 expression and tumor-infiltrating immune cells are still unknown." (PMID 33173413, 2020). "However, a recent report showing CDC6-mediated inhibition of apoptosome formation through its binding onto cytochrome c-activated Apaf-1, probably explains why senescence emerges as the only tumor suppressor mechanism in our system." (PMID 29321003, 2018). "Indeed, overexpression of Cdt1 and Cdc6 in mouse models has been shown to induce tumours." (PMID 22084381, 2011). "We also noted that CDDP-treatment of pxn100 tumours induced the expression by >2.5-fold of genes encoding proteins that regulate the G2M cell cycle checkpoint (WEE1, CCNB1, CDC25C) and a gene encoding a protein involved in the anaphase promoting complex in mitosis (CDC6)." (PMID 15452549, 2004). "Collectively, these findings demonstrate that PRDM1 acts as a tumor suppressor in BCa by inhibiting OTUD6A transcription and promoting CDC6 degradation." (PMID 41724787, 2026). "The CDC6 promoter served as a typical example of a cell cycle-related gene promoter, while the ARF and TAp73 promoters represented tumor suppressor genes." (PMID 41511373, 2026). "Mechanistically, experimental evidence reveals that CDC6 in tumor cells orchestrates fibroblast senescence via TGF‐β1 secretion and oxidative stress, subsequently reprogramming the tumor microenvironment and modulating ICI response." (PMID 39739618, 2025). "Depletion of OTUD6A inhibits CDC6 expression as well as BBN-induced BCa tumorigenesis and tumour progression." (PMID 38685067, 2024). "The results revealed that in tumor tissues from ccRCC patients, POLQ expression positively correlated with the expression of CDC6, CDC45, CDT1, FANCD2, and MCM2." (PMID 38270643, 2024). "The results showed that the expression of ACACB, ATP8B4, C14orf28, CIRBP, and DTWD1 were higher in normal tissues, and the content of CDC6, DSP, HMGB3, HNRNPA3P1, PPP1R14C, and TPX2 were higher in tumor tissues." (PMID 35778922, 2022). "Eight hub genes (CDK1, EGFR, UBC, MYC, CCNB1, RHOB, CDC6, and CDC20) have tumor suppressor functions, while five hub genes (CDK1, EGFR, FYN, UBC, and CCNB1) are protein kinases as well." (PMID 35632527, 2022).
tumor (continued). "In tissue microarray, CDC6 and MCM3 protein expression were significant differences by the immunohistochemistry-based H-score between tumor tissues and adjacent tissues, and CDC6 is an independent prognostic factor for GC." (PMID 35537781, 2022). "As expected, CDC6 was over expressed in HCC tissues and tumor cell lines compared to counterparts using RT-qPCR and IHC assays." (PMID 33173413, 2020). "Aberrant expression of CDC6 inducesseveral oncogenic properties in vitro, such as DDR activation,cellular transformation, and genomic instability, as well as tumor growthin vivo." (PMID 31930281, 2019). "In association with CDK2, Cyclin E controls DNA replicationthrough phosphorylation of multiple proteins, such as the RB tumor suppressorand the DNA replication factors CDT1, CDC6, and Treslin." (PMID 31930281, 2019). "Subsequent to validating the efficacy of CDC6 induction in the newly formed HBEC CDC6 Tet-ON system, we constitutively expressed it at levels relevant to those of tumor samples and monitored the cellular behavior over time." (PMID 29321003, 2018). "Core promoters with adjacent regions of the human genes CDC6, POLD1, CKS1B,MCM2, and PLK1 were cloned into a pGL3 vector in front of the Photinus pyrailsgene Luc in order to study the tumor specificity of the promoters." (PMID 24303203, 2013). "Furthermore, to comprehensively investigate the molecular characteristics of tumor-immune interactions, we utilized the TIMER analysis to assess the relationship between CDC6 and the degree of infiltration of multiple immune cells in SKCM." (PMID 39052109, 2024). "Likewise, we looked into HPV-positive HNSCC tumours with different grades in the TCGA and found that higher grade tumours appeared to have higher expression of BRD4, CDKNA2, RAD51AP1 and CDC6 with EGFR expression was lesser in higher tumour grades." (PMID 36333293, 2022). "According to TCGA and ICGC databases, we found CDC6 expressed highly in tumor tissues compared with adjacent normal tissues." (PMID 34136398, 2021). "Moreover, CDC6 inhibits E-cadherin expression, and overexpression of CDC6 can promote EMT and tumor development." (PMID 33316778, 2020). "Immunohistochemical stainings of cyclin E, MCM2, VEGF, CDC6 and BCL2 were performed in tumor tissues, and the staining intensities of cyclin E, MCM2, CDC6 and BCL2 were decreased in the GBK treatment group in xenograft-tumor mice compared to the control group." (PMID 28467790, 2017). "More positive-Cdc6 samples were detected in muscle invasive tumor samples (T2-T4, 75.6%) than in non-muscle-invasive tumor samples (Ta-T1, 57.6%), but with no significant statistical differences (P=0.055)." (PMID 27246979, 2016). "Cdc6 and immunoprecipitated E2F1 were also positively correlated with tumor mass." (PMID 27077880, 2016). "In order to know whether cdc6 can be observed in stem cells, and their influence on this study, we detected the expression of cdc6 mRNA in the PBMC from cord blood and health individuals, cell mixture of PBMCs and tumor cells, and tumor cells with RT‐qPCR." (PMID 32249466, 2020). "Furthermore, we used RT‐qPCR to test the cdc6 expression in PBMCs from tumor patients (test group) and non‐tumor individuals as a control group." (PMID 32249466, 2020). "In comparison, the ratios of negative and weak CDC6-expressing tumors (IHC score 0 to 4) remarkably decreased, but the ratios of strong Ki67-expressing positive tumors (IHC score 5 to 9) significantly increased in the CR tumor tissues." (PMID 30158672, 2019).
tumor (continued). "In addition, we measured the expression of a number of other genes in the tumours including nuclear receptors (VDR, RXRα, SXR, ER α and β), cytochrome P450 enzyme (CYP3A4), proliferation marker (MCM2, CDC6, KI67), differentiation marker (sucrase isomaltase) and angiogenesis marker (CD31)." (PMID 26238339, 2016). "Moreover, the protein but not the mRNA level of CDC6 was decreased in OTUD6A-knockdown T24 tumours." (PMID 38685067, 2024). "Among 232 Chinese GC patients, validation through immunohistochemical methods showed that the protein levels of CDC6 and MCM3 in tumor and nontumor tissues had significantly different histochemistry scores (H-scores)." (PMID 35537781, 2022). "RRM2 showed no expression in both normal and tumor tissues, while CDC45, and CDC6 were mainly expressed in tumor cells and immune cells." (PMID 32969465, 2020). "Like CDC6, the ANOVA test revealed that there was no statistically significant overall correlation of CDT1 mRNA level with tumor size (p = 0.43), lymph node status (p = 0.200), clinical stage (p = 0.221) or histological grade (p = 0.215)." (PMID 19116018, 2008). "According to the CPTAC data, the protein expression of PKMYT1, ETF1, ECT2, BUB1B, and RECQL4 in tumor tissues was significantly increased, while the expression of TFRC was significantly reduced, and the expression of COCH and TUBB2B did not change significantly (PITX1 and CDC6 were not included)." (PMID 33869220, 2021).
adenocarcinoma (2 papers, 2020). A common cancer characterized by the presence of malignant glandular cells. "Indeed, Cdc6 protein is expressed in both cervical squamous carcinoma and adenocarcinoma and is upregulated possibly due to E7-mediated release of E2F inhibition upon Rb binding, since Cdc6 is an E2F responsive gene." (PMID 33154944, 2020).
infection (2 papers, 2012). The state of being infected such as from the introduction of a foreign agent such as serum, vaccine, antigenic substance or organism. "Such an increase in Cdc6, could reflect a requirement for this cellular factor during infection." (PMID 22586460, 2012). "In this study, we have used siRNA knockdowns of Cdc6, Cdt1, ORC2 and MCM7 to address their role, if any, in HCMV DNA replication and show that infection of cells depleted for these proteins results in enhanced viral lytic DNA replication." (PMID 22586460, 2012). "Consequently, we next asked whether removal of cellular proteins such as Cdt1 and Cdc6, which are responsible for licensing cellular replication origins by recruiting MCM proteins, had any effect on infection." (PMID 22586460, 2012).
benign tumors (1 paper, 2021). "Several types of oncogenes have been reported to induce senescence in normal fibroblasts or benign tumors after over-expression, including Raf, cyclin E, mos, cdc6, E2F, Akt." (PMID 34552037, 2021).
Cell proliferation disorders (1 paper, 2023). "Cell proliferation disorders (Association score: 0.82, 64 diseases) are the most common causes of CDC6-related diseases." (PMID 36599883, 2023).
CDC6 also shares sentences with these, for which no sentence is quoted: mantle cell lymphoma (3 papers); primordial dwarfism (3); chronic myelogenous leukemia (2); dwarfism (2); genetic diseases (2); acute myeloid leukemia (1); adenoma (1); allergic asthma (1); anemia (1); astrocytomas (1); Azoospermia (1); cardiovascular disease (1); cervical (1); cholangiocarcinoma (1); diffuse large B-cell lymphoma (1); dysplasia (1); Epileptic encephalopathy (1); Hypertension (1); leukemia (1); lupus nephritis (1); lymph node metastasis (1); neurodegenerative disease (1); neurologic disease (1); non-Hodgkin lymphoma (1); pancreatic adenocarcinoma (1); pertussis (1); polycystic ovary syndrome (1); prion disease (1); pulmonary disease (1); rectal cancer (1).
A further 11 diseases each share a sentence with CDC6 in 1 paper.